PDC (phosducin)
Diseases named in the same sentence as PDC in open-access papers (continued):
Sharing a sentence is not in itself a finding about the gene and the disease.
psoriasis (continued). "Evidences suggest that pDC can be detected in the spleen, lymph nodes, and blood but is almost undetectable in normal skin, however, when it infiltrates into the skin, it plays a crucial role in the initial stage of psoriasis by secreting large amounts of IFN-α." (PMID 33488612, 2020). "The future identification of specific genetic variants potentially involving pDC activation and/or type I IFN signaling may provide an explanation for an increased susceptibility of these individuals to develop paradoxical psoriasis in the context of anti-TNF treatment." (PMID 29295985, 2018). "pDC cell activation is crucial in psoriasis pathogenesis as proven by a murine model of psoriasis wherein the development of skin lesions is inhibited by anti-BCDA-2 antibody, which suppresses pDC activation and, thus, IFN-α production." (PMID 29316717, 2018). "While pDC are considered to play a vital role in the development of psoriatic lesions, DDC are thought to be of major importance in the more chronic phase of psoriasis." (PMID 24744755, 2014). "Tissue infiltration of activated pDC has been reported in skin lesions of SLE, psoriasis, and systemic sclerosis patients, salivary glands of Sjögren’s disease patients, and muscles and skin of juvenile dermatomyositis patients." (PMID 24744755, 2014). "Unbiased transcriptomic analysis identified a distinct pDC cluster in patients with psoriasis, atopic dermatitis and other rashes, but not in healthy skin." (PMID 40796660, 2025). "Increased infiltration of pDC is observed not only in lesional skin but also in non-lesional skin of psoriasis patients, compared to normal skin from healthy controls." (PMID 35837394, 2022). "Because anti-TNF treatment in wild-type mice increases pDC accumulation and type I IFN production in the skin, we determined whether it also induced a psoriasis-like phenotype." (PMID 29295985, 2018). "In contrast to psoriasis, there seems to be no role for pDC in AD pathogenesis, since they are virtually absent from AD lesions like in healthy skin." (PMID 24744755, 2014). "Conversely, the immunological patterns typical of paradoxical psoriasis by anti-TNF-α and acute psoriasis, including overexpression of innate immunity molecules and dermal infiltration of BDCA+ pDC, CD15+ neutrophils, and c-kit/CD117+ mast cells could not be found." (PMID 38495872, 2024).
autoimmune disease (19 papers, 2009 to 2022). A disorder resulting from loss of function or tissue destruction of an organ or multiple organs, arising from humoral or cellular immune responses of the individual to their own tissue constituents. "Therefore, our study provides insights into the genetic control of pDC function and a paradigm for applying genetic variants to improve targeted therapy for autoimmune diseases." (PMID 35788118, 2022). "Finally, IRF8R294C mutant mice thus can be used as a model to elucidate the pDC functionality for designing therapeutic strategies of several autoimmune diseases where pDC dysregulation is associated with worse prognosis." (PMID 34867997, 2021). "Our study identifies CXCR4 as a potential modulator of pDC activity and therefore as a promising therapeutic target in autoimmune diseases and chronic infections." (PMID 28181493, 2017). "pDC infiltration has been documented in multiple pathological lesions including infections, tumors, and autoimmune diseases, and the severity of pDC infiltration correlates with disease progression." (PMID 27340692, 2015). "Numerous studies elucidate pDC function in different types of infection, autoimmune disease entities and in maintenance of tolerance [reviewed in Ref." (PMID 24904586, 2014). "Is-there a role for herpesvirus-dependent pDC activation in the triggering of certain autoimmune diseases?" (PMID 21994554, 2009). "The exact roles of pDC in most autoimmune diseases are still far from elucidation." (PMID 32489664, 2020). "Due to their highly efficient IFN-α producing capacity it was obvious that pDC might be involved in autoimmune disease." (PMID 24904586, 2014). "Because chronic IFN-I or TNF-α responses often occur in a variety of autoimmune diseases, it will be worth examining whether pDC activation by herpesvirus infections may contribute to the development of autoimmunity." (PMID 21994554, 2009). "As abnormal pDC activation and deregulated IFN-I production appear to be contributing factors in autoimmune disease pathogenesis, future studies should be performed to determine whether IFN-I blockade or pDC depletion would be an effective method for the treatment of autoimmune diseases." (PMID 29085361, 2017). "Indeed, pDC activation might be a double-edge sword for the host depending on the disease context, and its regulation represents a strategic issue in chronic infections and autoimmune diseases in which pDC are suspected to be hyperactive." (PMID 28181493, 2017). "Therefore, miRNAs are likely also involved in TLR-inhibited pDC apoptosis during GC treatment, and identifying these miRNAs will provide new targets for pDC-related autoimmune diseases and improve the efficacy of GC drugs for the control auto-inflammatory diseases." (PMID 23894561, 2013). "As some autoimmune diseases are characterized by aberrant frequencies of circulating pDCs and accumulation of pDCs in target organs or tissues, it will be interesting to determine whether the EBI2-7α,25-OHC axis plays a role in pDC migration/localization and activation of pathogenic pDC in tissues." (PMID 24386204, 2013). "Several groups reported that activation of pDC, followed by production of type-I interferons in absence of infection plays a role in the development of autoimmune diseases." (PMID 22952871, 2012). "Therefore, functional inhibition of pDCs through BDCA2 ligation in the absence of pDC depletion is a unique approach that could lead to both efficacy and a better safety profile in autoimmune diseases such as SLE." (PMID 25762615, 2015). "In addition to directly regulating pDC type I IFN responses through IRF7, EBI2 may also influence pDC responses by guiding their migration to and localization within lymphoid tissues or, in the case of autoimmune diseases, target organs." (PMID 24386204, 2013).
COVID-19 (19 papers, 2021 to 2025). A disease caused by infection with severe acute respiratory syndrome coronavirus 2. "Similarly, other inverse associations with active severe COVID-19 included pDC and Vδp T cells in the blood, which suggests the propensity of these immune cells to home to the lungs or other inflamed tissues during active severe COVID-19." (PMID 34867943, 2021). "To understand the cellular mechanisms leading to systemic IFN-I production during COVID-19, we investigated the mode of pDC activation and identified a novel pathway of macrophage-mediated pDC activation that was found to be extremely potent." (PMID 37253946, 2023). "As we found that pDC activation is a salient feature that negatively correlates with COVID-19 severity, we aimed to determine how contact with SARS-CoV-2-infected cells impacts the varied downstream signaling and function of pDCs." (PMID 36755036, 2023). "The proportion of ncMono, cDC and pDC declined prominently in COVID-19 patients compared to healthy controls." (PMID 37095364, 2023). "Considering the role of IFN-I and inflammatory cytokine responses in the severity of COVID-19, it is important to understand the cellular mechanisms and pathways involved in pDC activation." (PMID 37253946, 2023). "As expected, we observed a profound pDC depletion, in terms of both frequency and absolute numbers, in patients hospitalized with severe COVID-19 as compared to matched HD." (PMID 34473805, 2021). "However, there was a pronounced reduction in pDC frequency among COVID-19-positive women compared to Control-LS women (P<0.0001)." (PMID 41573558, 2025). "A recent study using humanized mice as a model for chronic COVID-19 provides supporting evidence for the hypothesis of macrophage-mediated pDC activation." (PMID 37253946, 2023). "Further, this study identified the failure of pDC response as critical in COVID-19 severity." (PMID 36755036, 2023). "Therefore, the contribution of pDCs to innate immune responses during COVID-19 and the mode of pDC activation in vivo should be investigated in future studies." (PMID 37253946, 2023). "Several studies showed that pDC number is reduced in COVID-19 patients." (PMID 36142877, 2022). "We first monitored whether the degree of COVID-19 severity would match to a differential level of circulating pDC and found a striking difference in the three analyzed groups." (PMID 34473805, 2021). "Interestingly, then, in a cohort of asymptomatic SARS-CoV-2-infected individuals circulating pDC were already reduced in the peripheral blood as respect to the healthy counterpart but significantly higher than what found in hospitalized COVID-19 patients." (PMID 34473805, 2021). "Although both mild and severe COVID-19 patients in our study displayed reduced frequency of pDC in blood, this reduction was significant only for severe COVID-19 patients, suggesting that additional mechanisms might be involved as well, like increased apoptosis in pDC." (PMID 33692788, 2021). "In our cohort, Control-LS individuals had significantly higher median pDC frequencies (75% higher; median of 0.20, IQR: 0.097-0.38) compared to COVID-19 patients (median 0.05, IQR: 0.015-0.11, P<0.0001)." (PMID 41573558, 2025). "Interleukin (IL)-6 concentrations were significantly increased in COVID-19 patients (p < 0.0001 vs. controls), and negatively correlated with the absolute counts of circulating CD1c+ cDC2 (r = −0.29, p = 0.034) and CD303+ pDC (r = −0.29, p = 0.036) subsets." (PMID 38731010, 2024). "Correlation analysis between IL-6 serum levels and the distribution of all DC subtypes further showed that in COVID-19 patients, IL-6 was negatively relatedto the circulating absolute levels of the CD1c+ cDC2 subpopulation (r = −0.29, p = 0.034) and CD303+ pDC subsets (r = −0.29, p = 0.036)." (PMID 38731010, 2024).
COVID-19 (continued). "Notably, the intercellular interactions signaling from pDC and those signaling to ncMono and pDC were reduced in severe COVID-19, implying that the dysfunction of the intercellular interactions involving these two subsets might be related to the severity of COVID-19." (PMID 37095364, 2023). "In addition, younger COVID-19 patients had higher proportions of CD169 expressing pDC and higher CD169 MFI as indicator of enhanced pDC activation." (PMID 34682920, 2021). "For instance, regardless of the disease severity, peripheral blood pDC and cDC1 counts were lowered in all COVID-19 patients, whereas an elevated cDC/pDC ratio might be considered a marker of a severe COVID-19 course." (PMID 36146713, 2022). "Importantly, pDC were found significantly reduced or absent in the blood of patients with severe COVID-19 and were absent in the lungs and in bronchoalveolar lavage fluids while showed a higher proportions in moderate disease." (PMID 34473805, 2021). "pDC showed a notable augmentation in BALF and depletion in PBMC in mild cases but not in severe cases, which may reflect the different migration activeness of pDC from blood to lung in mild and severe COVID-19." (PMID 34502134, 2021). "Importantly, while inflammatory monocytes and CD1c+ conventional DC were present in lung infiltrates of patients with severe COVID-19, CD123hi pDC were depleted in blood but absent in the lungs." (PMID 34473805, 2021). "Moreover, pDC have been extensively studied in patients with severe COVID-19 and were found significantly reduced or absent in the blood of these individuals." (PMID 34473805, 2021).
HIV-1 infection (14 papers, 2009 to 2018). The type species of lentivirus and the etiologic agent of acquired immunodeficiency syndrome (AIDS). "HIV-1 infection has been consistently shown to be associated with reduced frequency and impaired function of circulating pDC, both during primary and chronic infection." (PMID 19936055, 2009). "We conclude that pDC play two opposing roles during HIV-1 infection and pathogenesis: they produce IFN-I to inhibit HIV-1 replication, but enhance HIV-1 pathogenesis by promoting cell death of human leukocytes including human CD4 and CD8 T cells." (PMID 25077616, 2014). "During chronic HIV-1 infection, depletion of pDC also severely reduced the induction of IFN-I and ISGs, associated with elevated HIV-1 replication." (PMID 25077616, 2014). "Most surprisingly, depletion of pDC during chronic HIV-1 infection rescued human leukocytes including human CD4 T cells in lymphoid organs but not in blood, in spite of higher levels of HIV-1 replication." (PMID 25077616, 2014). "We have previously reported that human pDC are rapidly activated by HIV-1 infection in humanized mice and the level of pDC activation is correlated with CD4+ T-cell depletion." (PMID 25077616, 2014). "Increased apoptosis of pDC has also been reported in HIV-1 infection and is likely a driving force of pDC turnover." (PMID 24497833, 2014). "To define the role of pDC in HIV-1 infection and immunopathogenesis in vivo, we developed a monoclonal antibody that specifically and efficiently depletes human pDC in all lymphoid organs in humanized mice." (PMID 25077616, 2014). "Other lines of evidences have been reported to support a deleterious role of pDC activation during HIV-1 infection." (PMID 25400632, 2014). "To define the role of pDC in HIV-1 replication and immunopathogenesis during chronic HIV-1 infection, we performed pDC depletion during chronic HIV-JRCSF infection." (PMID 25077616, 2014). "A transient unresponsive state has also been observed during primary HIV-1 infection and in late stage HIV-1 infection, and was suggested to be a consequence of a refractory stage acquired following pDC activation in vivo." (PMID 24497833, 2014). "Using the humanized mouse model of HIV-1 infection and pathogenesis in vivo, we developed a novel pDC-specific mAb that specifically and efficiently depletes human pDC in various lymphoid organs in vivo." (PMID 25077616, 2014). "When pDC were depleted during chronic HIV-1 infection in humanized mice, pDC were still the major IFN-I producing cells in vivo, which contributed to HIV-1 suppression." (PMID 25077616, 2014). "In conclusion, findings presented in this study suggest that HIV-1 infection selectively impairs pDC and mdDC-mediated NK activation." (PMID 21408163, 2011). "We have previously shown that thymic pDC are necessary for the expression of MxA in response to HIV-1 infection of the thymus." (PMID 21904619, 2011). "As previously reported, in HIV-1 infection pDC depletion was more marked in the advanced disease stage." (PMID 19936055, 2009). "Worth noting, we found that in HIV-1 infection the levels of MxA expression directly correlated with viremia and were inversely related to the circulating pDC levels and the amount of IFN-α production upon in vitro TLR9 stimulation." (PMID 19936055, 2009). "Therefore, pDC are the critical IFN-I producer cells in response to acute HIV-1 infection, and they are required to significantly inhibit early HIV-1 replication." (PMID 25077616, 2014). "However, we found that the depletion of pDC abolished or dramatically reduced IFN-I production during acute or chronic HIV-1 infection, suggesting that pDC are the major IFN-I producing cells during both acute and chronic HIV infection in humanized mice." (PMID 25077616, 2014). "Therefore, persistent activation of pDC by HIV-1 infection in lymphoid organs contributes to HIV-1 immunopathogenesis by accelerating the death of all human leukocyte cells." (PMID 25077616, 2014).
HIV-1 infection (continued). "Thus, the humanized mouse model provides a relevant in vivo model for studying the role of pDC in HIV-1 infection and immunopathogenesis." (PMID 25077616, 2014). "Therefore, persistent pDC activation by HIV-1 infection contributes to HIV-1 induced depletion of human immune cells and leads to HIV-1 disease progression." (PMID 25077616, 2014). "The role of pDC in HIV-1 infection is not well understood and is still debating." (PMID 23243424, 2012). "The role of pDC and IFNα during HIV-1 infection has been a matter of intense debate." (PMID 20559432, 2010). "Summarized data further indicated that although HIV-1 infection led to a significant change of most of the genes with more than a 2-fold change, pDC depletion could attenuate the up-regulation of genes and restored the down-regulated genes to normal levels during chronic HIV-1 infection." (PMID 28759657, 2017). "In order to delineate the role of human pDC in HIV-1 infection and pathogenesis in vivo, we developed and screened a number of pDC-reactive monoclonal antibodies (mAb) and identified an anti-BDCA2 (CD303) mAb (15B), which could specifically deplete human pDC in lymphoid organs in humanized mice." (PMID 25077616, 2014). "The role of pDC in HIV-1 infection and immunopathogenesis, however, remains unclear." (PMID 25077616, 2014). "Thus, in the present study we investigated the fate and function of pDC in HIV-1 infection." (PMID 20559432, 2010). "We thus have demonstrated that pDC and IFN-I signaling plays a critical role in ILC1 depletion during chronic HIV-1 infection." (PMID 29304123, 2018). "In mice with a humanized immune system, pDC depletion strongly decreased ISG induction and enhanced viral replication both in the acute and chronic phases of HIV-1 infection." (PMID 25400632, 2014). "We report here that, in response to acute HIV-1 infection, pDC are the critical IFN-I producer cells and contribute to suppressing HIV-1 replication during early HIV-1 infection." (PMID 25077616, 2014). "Persistent activation of pDC and IFN-I have been correlated with HIV-1 infection induced immune activation both in HIV-infected patients and in SIV-infected rhesus monkeys." (PMID 25077616, 2014). "With this mAb, we were able to define the role of pDC in HIV-1 replication and immunopathogenesis during different phases of HIV-1 infection." (PMID 25077616, 2014). "In contrast to MFI, the frequency of BDCA-2+ pDCs is not influenced by HIV-1 infection, and in vitro activation of pDC via TLR7/9 agonists leads to downregulation of the pDC surface-localized BDCA-2." (PMID 29597250, 2018). "Thus we were able to characterize the role of human pDC in HIV-1 infection and immunopathogenesis during acute and chronic phases of HIV-1 infection." (PMID 25077616, 2014). "We discover that pDC are the critical IFN-I producer cells in response to acute HIV-1 infection, because depletion of pDC completely abolished induction of IFN-I or ISG by HIV-1 infection, correlated with elevated level of HIV-1 replication." (PMID 25077616, 2014). "Despite of higher level of viral replication in pDC-depleted mice, we found that HIV-induced depletion of human T cells and leukocytes was significantly reduced in lymphoid organs, correlated with reduced cell death induction by HIV-1 infection." (PMID 25077616, 2014). "The first studies reported that the number of circulating pDC was decreased in HIV-1 infection, and that the lack of IFN-α production was suggested to be responsible for HIV-1 disease progression." (PMID 23243424, 2012). "However, it is still not clear if pDCs are the major source of IFN-I during acute or chronic HIV-1 infection, and the role of pDC in HIV-1 replication or disease progression is not well defined." (PMID 25077616, 2014). "Thus pDC provide a possible pathway for R5 HIV-1 infection of thymocytes and may contribute to the changes in thymic output seen in HIV-1 infection." (PMID 21639903, 2011).
HIV-1 infection (continued). "In contrast, pDC depletion did not influence the percentages of CD34+CD38- early HPCs (CD38 expression) and their proliferation in vivo indicated by BrdU expression in the BM in the absence of HIV-1 infection." (PMID 28759657, 2017).